SALL4 (spalt like transcription factor 4)
Diseases named in the same sentence as SALL4 in open-access papers (continued):
Sharing a sentence is not in itself a finding about the gene and the disease.
hepatocellular carcinoma (continued). "STAT3 is one of the main regulators of SALL4 in breast cancer and hepatocellular carcinoma (HCC)." (PMID 36010677, 2022). "Recent evidence has indicated that SALL4, exhibiting progression-relevant expression, drives tumorigenesis, metastasis and radiochemotherapy resistance in gastric cancer, nasopharyngeal carcinoma and hepatocellular carcinoma." (PMID 32513235, 2020). "Some researchers have verified that SALL4, a protein expressed in fetal, but not adult, liver cells, was reexpressed in liver tissues of a subgroup of adult hepatocellular carcinomas, which is often associated with bad prognosis." (PMID 24860834, 2014). "According to a study on hepatocellular carcinoma (HCC), miR-497 directly targets SALL4 and negatively regulates its expression, contributing to the stemness properties and metastatic potential of HCC cells." (PMID 38584262, 2024). "Intriguingly, HK-2 has been previously shown to be downregulated in the microarray data of another study whereby SALL4 is knocked down in hepatocellular carcinoma (HCC) cells." (PMID 32489324, 2020). "Here, we show the first evidence that the inflammatory micro-environment promotes the stemness properties and metastatic potential of hepatocellular carcinoma (HCC) via the NF-κB/miR-497/SALL4 axis." (PMID 31650028, 2019). "FFW shows proapoptotic and antimigration effects in SALL4-expressing hepatocellular carcinoma (HCC) cells." (PMID 31231341, 2019). "Sal-like protein 4 (SALL4), a stem cell marker, has been identified as a potential target for aggressive hepatocellular carcinoma (HCC)." (PMID 26317546, 2015). "In hepatocellular carcinoma, the binding of SALL4 pseudogenes to DNMT1 and their impact on SALL4 expression have been investigated." (PMID 37627052, 2023). "Malignant melanoma expressed HMB45, MelanA, and S-100; small cell lung cancer expressed TTF-1, CD56, and CgA; hepatocellular carcinoma expressed GPC-3, hepatocyte, and Sall4." (PMID 37608278, 2023). "In hepatocellular carcinoma, SMARCA4 activates a series of downstream cascades by directly binding to the Sall4 promoter and enhancing Sall4 transcription, ultimately resulting in enhancing the stemness potency of cancer cells." (PMID 36674511, 2023). "The expression of hepatocellular carcinoma markers, including AFP, Arginase-1, Glypican-3 (GPC-3), SALL4, and Hep-1, provides valuable insights into the correlation with hepatocytes." (PMID 37950062, 2023). "Malignant melanoma expressed HMB45, MelanA, and S-100; small cell lung cancer expressed TTF-1, CD56, and CgA; hepatocellular carcinoma expressed GPC-3, hepatocyte, and Sall4; breast cancer expressed ER, PR, Her-2, and GCDFP-15." (PMID 37608278, 2023). "Furthermore, M2-polarization, which is more pro-tumorigenic, can be controlled by EVs derived from hepatocellular carcinoma (HCC) cells through SALL4/miRNA146a axis." (PMID 33260499, 2020). "As a subtype of hepatocellular carcinoma (HCC) markers, SALL4 is related to the prognosis of liver cancer." (PMID 28819584, 2017). "SALL4 is part of the Wnt signalling pathway and regulates the stemness of EPCAM-positive hepatocellular carcinomas." (PMID 27534621, 2016). "The data from another study also emphasized SALL4 expression was completely negative in hepatocellular carcinoma." (PMID 24860834, 2014). "In hepatocellular carcinoma (HCC) cells, the expression of GLUT1 is upregulated by spalt-like transcription factor 4 (SALL4) in a heterochromatin protein 1α (HP1α)-dependent manner, which confers doxorubicin (DOX) resistance to HCC cells by enhancing DNA damage responses." (PMID 40264038, 2025). "Most of these 22 studies were carried out in Asia (n=18), three in USA, and one in Europe, mainly focusing on hepatocellular carcinoma (HCC) (n=11) and SALL4 was mainly assayed by IHC (n=18) rather than by molecular tests (n=6)." (PMID 28160555, 2017).
hepatocellular carcinoma (continued). "Here we show a close negative correlation between SALL4 or PD-L1 and miR-200c in tumors from 98 patients with HBV-related hepatocellular carcinoma." (PMID 29593314, 2018).
breast cancer (40 papers, 2011 to 2024). A primary or metastatic malignant neoplasm involving the breast. "Given that CD44 has 9 variant exons and the regulation of the expression of these exons is complex, SALL4‐regulated KHDRBS3 expression seems to be one of the factors for CD44 variant expression in basal‐like breast cancer." (PMID 29356399, 2018). "High expression of SALL4 also is linked to chemo-resistance of breast cancer cells." (PMID 36010677, 2022). "However, studies on the roles of Nodal and SALL4 in tamoxifen resistance are limited and, to our knowledge, there is no published article on the association between the expression of Nodal and SALL4 in ER+ breast cancers." (PMID 34476264, 2021). "An aberrant SALL4 activity has been reported in acute myeloid leukemia, lung adenocarcinoma, breast cancer, and other aggressive malignancies, and its overexpression is associated with poor prognosis and lower survival rate of patients." (PMID 38062245, 2024). "SALL4 cytoplasmic marking has also been demonstrated in breast cancer cells and is considered a predictor of poor prognosis." (PMID 37559082, 2023). "SALL4 induced epithelial-mesenchymal transition and promoted tumor progression in breast cancer by directly binding to the vimentin promoter." (PMID 37525212, 2023). "Taken together, SALL4 is a determinant factor in breast cancer cell stemness, proliferation, and invasion, because of which its function as a therapeutic target needs to be further investigated in prospective studies." (PMID 36010677, 2022). "The basal-like breast cancer cells express high levels of SALL4 through which the alternative splicing of CD44 is modulated." (PMID 36010677, 2022). "SALL4 also regulates the tumorigenicity of breast cancers by modulating the Wnt3a/β-catenin signaling pathway." (PMID 35216168, 2022). "Knockdown SALL4 can induce cell apoptosis, suppress the cell proliferation, and reduce the invasion and migration ability of breast cancer cells." (PMID 35619068, 2022). "In basal-like breast cancer cells, SALL4 upregulates expression of cell migration related integrin genes ITGA6 and ITGB1." (PMID 36010677, 2022). "It is demonstrated that the degree of SALL4 expression is significantly related to tumor size and invasion to lymph nodes in breast cancer patients." (PMID 36010677, 2022). "miR-33b has a binding site in 3′ untranslated region (UTR) of the SALL4 mRNA and inhibits it in breast cancer cells." (PMID 36010677, 2022). "SALL4 regulates integrins β1 and α6 expression in basal-like breast cancer cells, a cell type with high migratory properties." (PMID 36438565, 2022). "Subsequently, overexpression of SALL4 was reported in a variety of cancers, such as breast cancer, lung cancer, liver cancer, endometrial cancer, germ cell cancer, as well as GC." (PMID 33644042, 2021). "Combining miRNA targets prediction database and qRT-PCR validation, the authors identified SALL4 as one of top miR-33b targets in breast cancer." (PMID 34573282, 2021). "On the contrary, SALL4 accelerated cell cycle progression in cervical, lung, and breast cancer cells, as well as in esophagus squamous cell carcinoma and glioma." (PMID 34944911, 2021). "In breast cancer cells, SALL4 expression is inversely correlated with that of the EMT marker ZEB1, as well as CDH1." (PMID 34441397, 2021). "Meanwhile, through inhibition of SALL4, miR-33b also suppressed metastasis of breast cancer in vivo." (PMID 34573282, 2021). "SALL4 is upregulated in various cancers, including gastric cancer, renal carcinoma, leukemia, and breast cancer." (PMID 34476264, 2021). "In this study, we tried to investigate the impact of the expression of SALL4 and Nodal on clinicopathological features and clinical outcome in ER+ tamoxifen-treated breast cancer patients." (PMID 34476264, 2021). "We evaluated the relationship between the expression of SALL4 and Nodal with the clinicopathological features of breast cancer patients by logistic regression." (PMID 34476264, 2021).
breast cancer (continued). "The SALL4 level in metastatic lymph nodes pertinent to the primary site is a considerable survival prognosis marker in breast cancer." (PMID 34476264, 2021). "Nevertheless, a recent study from 371 breast cancer patients showed that SALL4 expression positively correlates with PR protein level." (PMID 34944911, 2021). "Several independent studies suggest that SALL1, SALL2, and SALL4 play a role in the origin, progression, and response to breast cancer therapy." (PMID 34944911, 2021). "Downregulation of SALL4 suppresses cell proliferation and induces cell cycle arrest in acute myeloid leukemia, breast cancer and endometrial cancer." (PMID 32513235, 2020). "The regulation of cell adhesion molecules such as integrin by SALL4 has been previously reported in breast cancer cells." (PMID 32489324, 2020). "HMGA2, SALL4, and Twist1 are overexpressed in breast cancer, facilitating the self-renewal of CSCs, and enlarging the population of CSCs, leading to the tumor acquiring a higher invasive and metastatic ability." (PMID 31861404, 2019). "We therefore determined SALL4 gene expression in breast cancer cell lines and primary cancer tissues." (PMID 29625565, 2018). "Here, we revealed that a stem cell transcription factor, SALL4, functions to enhance stemness in basal‐like breast cancer cells." (PMID 29356399, 2018). "Our study showed that SALL4 was up-regulated in the drug resistant breast cancer cell line, MCF-7/ADR, compared to the other five cell lines." (PMID 26935744, 2016). "In the present study, we analyzed the involvement of an oncofetal gene, sal-like 4 (SALL4), in the tumor proliferation and drug resistance of human breast cancer." (PMID 26935744, 2016). "SALL4 knockdown inhibits the growth of the drug resistant breast cancer due to cell cycle arrest and reverses tumor chemo-resistance through down-regulating the membrane transporter, BCPR." (PMID 26935744, 2016). "This novel finding in MDBMSCC is consistent with previous studies reporting on cytoplasmic expression of NANOG in cervical cancer and SALL4 in breast cancer cells, inferring cytoplasmic expression as a predictor of poor prognosis." (PMID 27532037, 2016). "Our data demonstrated that miR-33b dramatically downregulated the expression of HMGA2, SALL4 and Twist1 in breast cancer cells to suppress cell self-renewal." (PMID 25919570, 2015). "We also analyzed cDNA microarray data in Oncomine34 to further confirm the role of HMGA2, SALL4 and Twist1 in breast cancer pathogenesis." (PMID 25919570, 2015). "Some investigators had confirmed that SALL4 is also overexpressed in cells from breast cancer, Yolk Sac tumor, non-small cell lung carcinomas (NSCLC), and testicular germ tumors." (PMID 24860834, 2014). "At the meaning time, some other kinds of tumor such as colorectal cancer, breast cancer, and Wilms tumors also express SALL4." (PMID 24860834, 2014). "In breast cancer, it is demonstrated that 86.1% of tumor samples showed elevated levels of SALL4 mRNA expression, where the increased levels of SALL4 mRNA expression were observed even in the early stages of tumors." (PMID 23363002, 2013). "A high expression of SALL4 is known in various tumors, such as breast cancer and HCC." (PMID 38355684, 2024). "In addition, degradation of spalt-like transcription factor 4 (SALL4), a transcription factor that promotes breast cancer cell proliferation and migration, is regulated by TRIM21/Ro52, and thus higher levels of TRIM21/Ro52 can reduce SALL4 levels." (PMID 37993883, 2023). "The oncogene Bmi-1 also is overexpressed by SALL4 in breast cancer cells." (PMID 36010677, 2022). "Interestingly, SALL4, the oncogenic member of the SALL family, is associated with increased cell migration and invasion in gastric and breast cancer cell lines." (PMID 36438565, 2022). "SALL4 modulates stemness of breast cancer cells through different mechanisms." (PMID 36010677, 2022).
breast cancer (continued). "Knock down of SALL4 by siRNA is shown to induce apoptosis in colorectal and breast cancer cells." (PMID 36010677, 2022). "We found higher SALL4 expression in breast cancer tissues compared to healthy tissue." (PMID 36362083, 2022). "The upregulation of SALL4 and Nodal has been reported in breast cancer." (PMID 34476264, 2021). "PR was related to breast cancer stemness in vitro, similar to SALL4." (PMID 34944911, 2021). "Interestingly, SALL4 associates with Nanog, OCT4, and Sox2 to enable breast cancer cells to acquire stem‐cell‐like and metastatic properties." (PMID 34476264, 2021). "Intriguingly, miR-33b could repress self-renewal of breast cancer cells, which is one of the main functions of SALL4." (PMID 34573282, 2021). "This study has tried to examine the mRNA expression of Nodal and SALL4 in tamoxifen sensitive and tamoxifen-resistant breast carcinomas to discover whether they have any effect on resistance during tamoxifen therapy." (PMID 34476264, 2021). "SALL4 is also required for cell proliferation, invasion, and maintenance of pluripotency of stem cells in embryonic stem cell and malignantly transformed stem cells, such as leukemia, breast cancer, and liver cancer." (PMID 29691367, 2018). "SALL4 is also expressed in basal‐like breast cancer cell lines." (PMID 29356399, 2018). "In conclusion, this study suggests that knockdown of SALL4 inhibits the proliferation of MCF-7/ADR cells through arresting the cell cycle in the G1 phase and that down-regulation of SALL4 reverses the drug resistance of breast cancer by reducing the expression of ABCG2 and c-myc." (PMID 26935744, 2016). "In addition, miRNA can act pleiotropically; therefore, HMGA2, SALL4 and Twist1 are the ideal targets of miR-33b in modulating the stemness of breast cancer cells." (PMID 25919570, 2015). "Serial reports have shown that SALL4 is required for cell proliferation and maintenance of pluripotency in several types of stem cells, as well as in malignantly transformed stem cells (e.g. leukemia and breast cancer)." (PMID 26317546, 2015). "Silencing of SALL4 in breast cancer cell line, MCF7, inhibits its propagation." (PMID 23363002, 2013). "However, there was not any significant correlation between clinicopathological features of the patients and SALL4 mRNA expression in breast cancer." (PMID 23363002, 2013). "We have also observed the expression of SALL4 in breast cancer as reported." (PMID 21526180, 2011). "In addition to liver cancer and NSCLC, both SALL4 and Let-7 family microRNAs have been shown to play important roles in the pathogenesis of multiple cancer types, such as glioma, ovarian cancer, colorectal cancer, breast cancer, and myeloid neoplasms." (PMID 34573282, 2021). "Therefore, we are interested in determining whether P-gp, BCRP and c-Myc are related with SALL4 involved in chemotherapy resistance in breast cancer." (PMID 26935744, 2016). "Thus, SALL4 has potential as a novel target for the treatment of breast cancer." (PMID 26935744, 2016). "SALL4 and GNAS were known to promote breast cancer progression, and previously reported to be involved with SE hijacking events." (PMID 39322849, 2024). "KHDRBS3 is upregulated by SALL4 as a splicing factor for CD44, which enhances stemness in breast cancer cells." (PMID 37848941, 2023). "Some studies have suggested that SALL4 silencing in Dox BC resistance cell lines reverts the resistance through cell cycle arrest and downregulation of membrane transporter ABCG2, more commonly referred to as BCRP (breast cancer resistance protein) and nuclear receptor-binding protein 1 (NRBP1)." (PMID 36362083, 2022). "Functionally, SALL4 knockdown inhibited cell proliferation and induced the G0/G1 cell cycle arrest of MDA breast cancer cells, an effect explained by the SALL4 positive regulation of the Wnt/β-catenin pathway in breast tumors." (PMID 34944911, 2021).
breast cancer (continued). "Altogether, studies suggest that in breast cancer, SALL1 and SALL4 are involved in migration, invasion, and EMT by regulating common targets such as E-cadherin and vimentin, but in an opposite manner." (PMID 34944911, 2021). "Silencing of SALL4 in lung cancer and MCF-7 breast cancer cells, increased their sensitivity toward anti-cancer drugs." (PMID 34476264, 2021). "SALL4 also promoted leukemogenesis by repressing the tumor suppressor PTEN, similar to its breast cancer function." (PMID 34944911, 2021). "SALL1 is bound to the NuRD complex in breast cancer; thus, it is likely that SALL1 and SALL4 share a similar repressive mechanism for PTEN regulation." (PMID 34944911, 2021). "SALL4 re-expression is recognized in various cancers and is considered an adverse prognostic factor in HCC, breast cancer, and lung cancer." (PMID 30989433, 2019). "As for the stemness of basal‐like breast cancer, our KHDRBS3 overexpression experiments showed prevention of the reduction in sphere formation ability by SALL4 knockdown." (PMID 29356399, 2018). "We used a basal‐like breast cancer cell lines SUM159 and Hs578T, and observed reduced sphere formation ability in SALL4 knockdown cells." (PMID 29356399, 2018). "The mechanism through which miR-33b inhibits the stemness, migration and invasion of breast cancer cells is by targeting HMGA2, SALL4 and Twist1." (PMID 25919570, 2015). "Collectively, these data indicate that miR-33b can inhibit breast cancer stem-like cell self-renewal by targeting HMGA2, SALL4 and Twist1." (PMID 25919570, 2015). "The ectopic expression of miR-33b downregulated the expression of ADAM9, HMGA2, LDHA, SALL4, SNAI2 and Twist1 by more than 30% but had minimal effects on HIF-1α, RAC1, Yes1 and ZEB1 in these two breast cancer cell lines." (PMID 25919570, 2015). "miR-33b can inhibit the self-renewal of breast cancer cells and their migration and invasion capabilities by targeting HMGA2, SALL4 and Twist1." (PMID 25919570, 2015). "In addition to SALL4 and SALL2, studies in breast cancer lines showed that SALL1 inhibition increases cell migration and correlates with decreased cadherin 1 expression." (PMID 36438565, 2022). "For example, in breast cancer cells, SALL2 is downregulated, but SALL4 is upregulated." (PMID 36438565, 2022). "Unlike SALL1 and SALL2, studies showed higher SALL4 expression in breast cancer cell lines and primary tissues than their non-tumoral counterparts." (PMID 34944911, 2021). "This indicates that although other splicing factors might function to regulate CD44 alternative splicing under the control of SALL4, the SALL4 ‐ KHDRBS3 network contributes to stemness in basal‐like breast cancer." (PMID 29356399, 2018). "In contrast to SALL1 gene expression, we found significantly higher expression of SALL4 in both breast cancer cell lines and primary cancer tissues, suggesting that SALL1 and SALL4 may have distinct functional roles in the regulation of breast cancer." (PMID 29625565, 2018). "Nevertheless, studies on the relation between SALL4 and drug resistance and chemotherapeutic sensitivity in breast cancer are still lacking." (PMID 26935744, 2016). "Moreover, SALL4 is enriched in SP in breast cancer cell line MCF7 along with ABCA3 and ABCG2, and increased SALL4 expression led to an expansion of SP in MCF7 cells." (PMID 21526180, 2011). "Moreover, we found that miR-33b does not alter the 3′UTR activity of the well-established EMT transcription factor SNAI2, suggesting that miR-33b regulates HMGA2, SALL4 and Twist1 in breast cancer cells without impacting EMT." (PMID 25919570, 2015). "(A) Transfection of SALL1, but not SALL4 in MCF-7 and E0771 breast cancer cells significantly induced the increased SA-β-Gal+ cell populations." (PMID 29625565, 2018). "However, we observed no significant change in the total CD44 expression level by SALL4 knockdown, indicating that SALL4 does not regulate CD44 transcription in basal‐like breast cancer cells." (PMID 29356399, 2018).